DUX4 (double homeobox 4)
Diseases named in the same sentence as DUX4 in open-access papers (continued):
Sharing a sentence is not in itself a finding about the gene and the disease.
colon cancer (3 papers, 2020 to 2022). "NFE2L3 functioned as an oncogene in colon cancer by suppressing the expression of DUX4, which functioned as a direct inhibitor of CDK1." (PMID 35059466, 2022). "DUX4 was shown to inhibit CDK1 activity, likely by preventing CDK1 binding to its targets and supporting a tumor suppressor function of DUX4 in colon cancer." (PMID 34943834, 2021). "Surprisingly, DUX4 appears to act as tumor suppressor in colon cancer and synovial sarcoma by multiple mechanisms." (PMID 34943834, 2021). "Aberrant DUX4 expression was recently reported to have a specific role in colon cancer." (PMID 34943834, 2021). "Repression of DUX4 gene expression was shown to be an important mechanism through which the transcription factors NF-kB and NFE2L3 regulate colon cancer cell proliferation." (PMID 34943834, 2021).
Duchenne muscular dystrophy (3 papers, 2017 to 2025). Duchenne muscular dystrophy (DMD) is a neuromuscular disease characterized by rapidly progressive muscle weakness and wasting due to degeneration of skeletal, smooth and cardiac muscle. "A recent study reported that Dux, the murine ortholog of DUX4, contributes to the dystrophic phenotype in mdx mice, a Duchenne muscular dystrophy (DMD) model, and that its deletion enhances muscle regeneration by reducing oxidative stress." (PMID 40422198, 2025). "In contrast to Duchenne Muscular Dystrophy (DMD), which results from loss of function mutations in the dystrophin gene, FSHD is linked to a gain of function of the DUX4 protein in skeletal muscles." (PMID 28273791, 2017). "Based on these findings, they further speculated that DUX4 might also contribute to Duchenne muscular dystrophy (DMD) pathology." (PMID 40422198, 2025). "Current research involves the use of antisense oligonucleotide therapies (ASOs) to target inactivation of DUX4, and the success of ASOs for Duchenne muscular dystrophy (DMD) and spinal muscular atrophy provide a regulatory pathway for those chemistries." (PMID 31506080, 2019). "Given that Dux has been proposed to contribute to the muscle phenotype in mdx mice, it has also been hypothesized that DUX4 may play a role in Duchenne muscular dystrophy (DMD)." (PMID 40422198, 2025).
embryonal rhabdomyosarcoma (3 papers, 2016 to 2025). A poorly circumscribed morphologic variant of rhabdomyosarcoma. "Finally, a DUX4 fusion event has also been implicated in embryonal rhabdomyosarcoma (ERMS), another soft tissue sarcoma in which the affected cells morphologically resemble the developing skeletal myocytes of the embryo." (PMID 40940582, 2025). "Recurrent DUX4 fusions have been detected in B cell acute lymphoblastic anemia, embryonal rhabdomyosarcoma, Ewing-like sarcomas and pediatric primitive round cell sarcomas." (PMID 27556182, 2016).
herpesvirus infection (3 papers, 2023 to 2025). "We demonstrate that herpesvirus infection induces the expression of the embryonic transcription factor DUX4, which subsequently activates its downstream target, SLC34A2, a phosphate transporter." (PMID 41211819, 2025). "DUX4 is functionally required for herpesvirus infection, since genetic depletion of DUX4 by CRISPR/Cas9 abrogates viral replication." (PMID 38168299, 2023). "Interestingly, previous studies have shown that herpesvirus infection induces TRIM43 in a DUX4-dependent manner and that TRIM43 restricts herpesvirus replication." (PMID 41211819, 2025). "TRIM43 is unique in that it is expressed at very low levels in uninfected cells; however, after herpesvirus infection, TRIM43 transcript and protein levels are drastically upregulated, which is mediated by the transcription factor DUX4 (Double Homeobox 4)." (PMID 39599852, 2024). "Here, we report that herpesvirus infection selectively activates the embryonic transcription factor DUX4 in human but not murine cells." (PMID 41211819, 2025). "Together with our prior findings that herpesviruses induce DUX4 specifically in human cells, these results suggest that the inability to induce Dux in murine cells during herpesvirus infection is a major reason for the absence of this immune evasion pathway in mice." (PMID 41211819, 2025).
lymphoma (3 papers, 2019 to 2024). A malignant (clonal) proliferation of B- lymphocytes or T- lymphocytes which involves the lymph nodes, bone marrow and/or extranodal sites. "B‐lymphoblastic leukemia/lymphoma (B‐ALL) with DUX4 rearrangement is a new provisional entity in the 5th edition of the World Health Organization Classification of Hematolymphoid Tumors which is more common in children, adolescents, and young adults and is associated with good prognosis." (PMID 38895089, 2024). "The TSSs of most NOVELG000070644 and NOVELG000059671 isoforms originate from insertions of THE1D, an LTR element of the ERVL-MaLR family, which are activated by DUX4 and have been shown to provide alternative promoters for multiple genes in placenta and lymphoma studies." (PMID 37903791, 2023). "Importantly, apoptosis suppressor lncRNA in Myc-driven lymphomas miR-17/92 cluster host gene (MIR17HG) is upregulated in relapsed samples within the Ph-like subtype and downregulated in relapsed samples within DUX4 and NH-HeH subtypes." (PMID 30642353, 2019).
metastatic tumors (3 papers, 2023 to 2024). "Resembling the cleavage stage embryo and DUX4-expressing primary cancers, DUX4-positive metastatic tumors transcribe the full-length coding region." (PMID 38829686, 2024). "Here, we report that DUX4 expression is a common feature of metastatic tumors, with ~10-50% of advanced bladder, breast, kidney, prostate, and skin cancers expressing DUX4." (PMID 37502871, 2023). "Strikingly, DUX4 expression is mostly a feature of metastatic tumors and correlates with a bad tumor prognosis, reducing survival rates about a year compared to DUX4-negative tumors." (PMID 37876935, 2023). "Since DUX4 expression in cancer cells suppresses MHC class I-mediated antigen presentation, we hypothesized that DUX4 expression might be particularly common in the setting of metastatic disease (vs. the primary cancers that we studied previously), where immune evasion is particularly important." (PMID 38829686, 2024).
urothelial carcinoma (3 papers, 2023 to 2025). A malignant neoplasm derived from the transitional epithelium of the urinary tract (urinary bladder, ureter, urethra, or renal pelvis). "We examined associations between global gene expression profiles and DUX4 expression in this advanced urothelial carcinoma cohort." (PMID 38829686, 2024). "DUX4 expression is significantly associated with immune cell exclusion and decreased objective response to PD-L1 blockade in a large cohort of urothelial carcinoma patients." (PMID 37502871, 2023). "We verified that DUX4 expression in the advanced urothelial carcinoma tumors was associated with an immune exclusion phenotype: a higher proportion of DUX4+ tumors exhibit either an immune-excluded or immune-desert phenotype compared to malignancies where DUX4 is silent." (PMID 38829686, 2024). "We used a Random Survival Forest (RSF) model to quantify the effect of DUX4 expression on survival in ICI-treated advanced urothelial carcinoma patients." (PMID 38829686, 2024). "Differentially expressed genes were identified from the comparison of advanced urothelial carcinoma tumors with high (>1 TPM) vs. low (≤1 TPM) DUX4 expression." (PMID 38829686, 2024). "Double homeobox protein 4 (DUX4) is characterized as a common driver of immune exclusion and contributes to a decreased objective response to anti-PD-L1 therapy in urothelial carcinoma patients." (PMID 41227363, 2025). "(B) Downregulated (blue) and upregulated (red) anti-tumor immunity genes in tumors with DUX4-positive (>1 TPM) vs. -negative (≤1 TPM) advanced urothelial carcinomas." (PMID 38829686, 2024). "(A) The proportion of clinical response classifications (RECIST, Response Evaluation Criteria in Solid Tumors) in DUX4-positive (DUX4+, >1 TPM) or -negative (DUX4−, ≤1 TPM) advanced urothelial carcinoma patients." (PMID 38829686, 2024).
metastatic cancers (2 papers, 2023 to 2024). A carcinoma which has spread from the original site of growth to another anatomic site. "We therefore analyzed several large cohorts of patients with different metastatic cancers to determine the frequency of DUX4 expression in advanced disease." (PMID 38829686, 2024). "A markedly higher proportion of advanced metastatic cancers express DUX4—and tend to have higher absolute DUX4 expression levels—than do their TCGA cancer counterparts." (PMID 38829686, 2024). "(D) Representative RNA-seq coverage plots from primary and metastatic cancers for reads mapping to the DUX4 cDNA." (PMID 38829686, 2024). "DUX4’s ubiquitous expression across metastatic cancers and our controlled survival analyses emphasize DUX4 as an underappreciated contributor to ICI resistance." (PMID 38829686, 2024). "Future studies could also investigate if the DUX4 gene could be a therapeutic target for mitigating resistance to immunotherapy in metastatic cancers." (PMID 38829686, 2024). "As these become available in the future, extending the analyses we have outlined in this study will be important to appraise DUX4’s definitive clinical relevance, contextualized among response-modifying clinical variables, in the use of immunotherapy in the treatment of metastatic cancer." (PMID 38829686, 2024). "First, urothelial cancers exhibited one of the highest frequencies of DUX4 expression (54% of patients) in any of the five metastatic cancer cohorts that we analyzed, suggesting that DUX4 could be particularly important in that tumor type." (PMID 38829686, 2024). "We next sought to assess the downstream consequences of DUX4 expression in metastatic cancers." (PMID 38829686, 2024).
muscle atrophy (2 papers, 2012 to 2013). The loss of muscle tissue due to inactivity or disease. "DUX4 overexpression induced hypomorphic myotube formation associated with the induction of E3 ubiquitin ligases (MURF1 and Atrogin1) typical of muscle atrophy, whereas RNA interference or antisense oligonucleotides targeting the DUX4 mRNA reversed this phenotype." (PMID 23206257, 2013).
muscular atrophy (2 papers, 2019 to 2024). "The expression of this aberrant DUX4 protein in muscle cells targets the expression of germline genes, immune mediators, and retroelements, alters the metabolism of RNA and proteins, and causes apoptosis of muscle cells, which eventually leads to muscular atrophy." (PMID 30794581, 2019).
nasopharyngeal carcinoma (2 papers, 2023 to 2025). A carcinoma arising from the nasopharyngeal epithelium. "We found a strong association between DUX4 expression and human papillomaviruses (HPV) in head and neck cancer samples as well as an association with EBV-positive nasopharyngeal carcinoma." (PMID 39814710, 2025). "We observe expression of DUX4 target genes in EBV-positive nasopharynx carcinoma cells, HPV-positive head and neck cancer and Merkel cell carcinoma, but not in healthy tissue from the same donors." (PMID 39814710, 2025). "nasopharyngeal carcinoma, we could further demonstrate that DUX4 target gene expression was only detected in EBV-pos." (PMID 38168299, 2023). "We observe expression of DUX4 target genes in EBV-positive nasopharynx carcinoma cells, but not in healthy tissue from the same donors." (PMID 38168299, 2023).
oligodendroglioma (2 papers, 2017 to 2023). A well-differentiated (WHO grade II), diffusely infiltrating neuroglial tumor, typically located in the cerebral hemispheres. "The CIC-double homeobox 4 (DUX4) fusion oncoprotein retains CIC DNA-binding specificity but gains activating capacity to increase ETV5 transcription, which is consistent with the overexpression of ETV5 in CIC-mutant oligodendrogliomas." (PMID 36872348, 2023).
osteosarcoma (2 papers, 2025). A usually aggressive malignant bone-forming mesenchymal neoplasm, predominantly affecting adolescents and young adults. "For example, valproic acid (VPA), a histone deacetylase inhibitor, has been shown to affect osteosarcoma progression by reprogramming cancer cells toward a more stem-like state through epigenetic modifications similar to those mediated by DUX4." (PMID 40427614, 2025). "Notably, pseudorabies virus (PRV) infection induced DUX4 expression in human osteosarcoma U2OS cells." (PMID 41211819, 2025). "Additionally, VPA treatment in osteosarcoma cell lines increases the expression of certain DUX4 target genes, suggesting a mechanistic overlap." (PMID 40427614, 2025).
skin cancer (2 papers, 2023 to 2024). "The analysis showed that DUX4 is reactivated in approximately 10–50% of advanced bladder, breast, kidney, prostate and skin cancers." (PMID 38829686, 2024).
asthma (1 paper, 2021). "The potential involvement of miR-31-5p in DUX4 downstream cascades is supported by the dysregulation of miR-31-5p in several inflammatory-related disorders such as cancer, psoriasis, experimental autoimmune encephalomyelitis, inflammatory bowel disease, lupus and asthma." (PMID 34338285, 2021).
Atrophy (1 paper, 2011). Any weakening or degeneration, especially through lack of use. "We now show that transfection of myoblasts with a DUX4 expression vector leads to atrophic myotube formation associated with the induction of E3 ubiquitin ligases (MuRF1 and Atrogin1/MAFbx) typical of muscle atrophy." (PMID 22053214, 2011).
autoimmune disease (1 paper, 2024). A disorder resulting from loss of function or tissue destruction of an organ or multiple organs, arising from humoral or cellular immune responses of the individual to their own tissue constituents. "Thus, muscle with chronic expression of DUX4 does not exhibit the increase in fiber MHC I expression that is typical of autoimmune diseases." (PMID 38340007, 2024).
Barrett syndrome (1 paper, 2021). "Moreover, our analysis highlighted DUX4 (Double Homeobox 4; OMIM 606009), which, when depleted, is related to muscle weakness or atrophy, one of the main characteristics of Guillaume-Barrett syndrome." (PMID 33466592, 2021).
breast tumor (1 paper, 2026). "Applying these resources to breast tumor, FSHD, and lymphoblastoid cell line datasets revealed that DUX4 is expressed in both breast tumor and FSHD tissues, whereas DUX4C shows expression only in breast tumors." (PMID 41540238, 2026).
cervical tumors (1 paper, 2009). "High frequency of DUX4 transcriptional down-regulation in cervical tumors is an additional indirect evidence for the putative protein-coding function of 3.3-kb repeats and an argument for further search for DUX proteins in normal somatic and embryonic tissues." (PMID 19473516, 2009).
germ-cell cell tumor (1 paper, 2010). "The large numbers and nuclear morphology of the cells staining with DUX4 in the seminiferous tubules, together with expression of DUX4 in the human germ-cell cell tumor lines SuSa and 833K (data not shown), leads us to conclude that DUX4 is expressed in the germ-line lineage." (PMID 21060811, 2010).
HCMV infection (1 paper, 2025). "Similarly, HCMV infection robustly upregulated DUX4 and its downstream genes in human HFFs." (PMID 41211819, 2025).
Hepatitis (1 paper, 2025). Inflammation of the liver. "Immunohistochemistry confirmed DUX4 expression in liver biopsies from HSV-1 hepatitis patients but not in hepatitis samples from hepatitis-B virus or in hepatitis-C virus infected liver samples." (PMID 39814710, 2025).
migraine (1 paper, 2025). "Finally, we prioritized potential migraine drug targets, including losmapimod (which reduces production of toxic DUX4 protein) and TLR4 antagonists." (PMID 41420111, 2025).
muscle hypertrophy (1 paper, 2016). "We validated interaction of DUX4 with the LIM and cysteine-rich domain 1 protein (LMCD1) that is known to play roles in cardiac muscle hypertrophy by targeting NFAT (Nuclear Factor Of Activated T-Cells)." (PMID 26816005, 2016).
myotonic dystrophy (1 paper, 2017). An inherited progressive disorder affecting the muscles. "In many cases DUX4-induced cells with EIF4A3 aggregates appeared to have reduced nuclear staining beyond the aggregates suggesting that the majority of EIF4A3 was redistributed to the dsRNA foci, similar to the depletion of MBNL proteins by the mutant nuclear RNA in myotonic dystrophy." (PMID 28273136, 2017).
neck cancer (1 paper, 2023). "In addition, we could show upregulation of DUX4 in single-cell RNA sequencing datasets of HPV-positive heck and neck cancer, indicating that DUX4 might also play a role in HPV infection." (PMID 37876935, 2023).
Obesity (1 paper, 2022). Accumulation of substantial excess body fat. "The DUX4 co-methylation network also showed several significant negative correlations with maternal blood markers during pregnancy that are known to be associated with obesity." (PMID 36130949, 2022). "Notably, the DUX4 DNA hypomethylation in FSHD directionally corresponds with the DUX4 co-methylation network we observed in hippocampus, where the maternal obesity with no intervention group was hypomethylated when compared to the control and obesity intervention groups." (PMID 36130949, 2022).
ocular tumour (1 paper, 2024). "For 56 of the ocular tumour-associated genes, excluding DUX4 due to insufficient data, the median of the haploinsufficiency variables was as follows: pLI of 0.72, O/E of 0.19 and pHaplo 0.89." (PMID 38388005, 2024).
polymyositis (1 paper, 2021). A rare idiopathic inflammatory myopathy characterized by symmetric proximal muscle weakness and elevated muscle enzymes. "DUX4 suppresses MHC class I in cancer, and so may also be protective in FSHD by preventing infiltration of non‐necrotic fibres by endomysial CD8+ T‐cell infiltrates, as occurs in polymyositis." (PMID 34151531, 2021).
Skeletal myopathy (1 paper, 2018). "While FLExDUX4 hemi- and homozygous mice express very low levels of DUX4-fl and display mild phenotypes in fur, digestive tract, and muscle fiber type, they show no signs of a skeletal myopathy and are generally healthy." (PMID 29415061, 2018).
small cell osteosarcoma (1 paper, 2022). "A recent study of small cell osteosarcoma identified 10/36 with a gene fusion involving DUX4 and CIC." (PMID 35887382, 2022).
tauopathies (1 paper, 2022). "Thus, to discriminate the two tauopathies, we hereby propose JUN(B,D)HIGH, FOS(L1,L2)HIGH as well as the involvement of DUX4, KLF5, MAX::MYC, PAX6, and PPARG to support the identity of CBD-originated astrocytes." (PMID 35976433, 2022).